PF4 (platelet factor 4)
Diseases named in the same sentence as PF4 in open-access papers (continued):
Sharing a sentence is not in itself a finding about the gene and the disease.
atherosclerosis (continued). "Compared to healthy control subjects, a higher level and rate of re-establishment of the extracellular PF4 has been demonstrated in several patient populations, including those with diabetes, atherosclerosis renal, cardiovascular or coronary artery disease." (PMID 23561460, 2013). "Platelet-derived PF4 plays major role in endothelial proliferation and endothelial cell apoptosis, angiogenesis, tumor development and atherosclerosis." (PMID 22792197, 2012). "PF4 promotes monocyte survival, induces monocyte differentiation into macrophages, and accelerates the formation of foam cells in atherosclerosis." (PMID 22662117, 2012). "Immune roles for PF4 are less well described, but likely more important given the global prevalence of vascular inflammatory diseases ranging from atherosclerosis to cerebral malaria." (PMID 20454664, 2010). "A previous study reported PF4 as a therapeutic target for atherosclerosis." (PMID 38271077, 2024). "Additionally, the roles of PF4 in cancer, atherosclerosis, and heparin-induced thrombocytopenia are well-established." (PMID 35720325, 2022). "Given the fact that PF4 inhibits progenitor cell proliferation and angiogenesis, its decreased expression in HUVECs might result in atherosclerosis promotion and therefore seems biologically plausible." (PMID 33574979, 2021). "It has been known that platelets are also involved in the development and manifestation of atherosclerosis by secreting chemokines including CXCL4 or platelet factor 4, CCL5, CXCL12 to recruit monocytes or neutrophils to promote local inflammatory processes at sites of vascular injury." (PMID 34901005, 2021). "PF4/heparin antibody formation may also be facilitated in other conditions characterized by elevated plasmatic PF4 levels such as diabetes, atherosclerosis, and cardiovascular and renal disease." (PMID 28698883, 2017). "There is no doubt that CXCL4 is important for atherosclerosis since the deletion of the PF4 gene that encodes CXCL4 reduces atherosclerotic lesions in apoE deficient mice." (PMID 24847266, 2014). "Platelets chemokines (e.g. RANTES, PF4, SDF-1, MCP-1, CXCL5, CXCL7) and newly synthesized active cytokine-like factors [e.g. IL-1β, CD40 ligand (CD40L), β-thromboglobulin] are implicated in the development of atherosclerosis." (PMID 23372649, 2013). "For another investigated factor, PF4, we obtained also the higher concentrations in platelet supernatants obtained from HH and HH-PMPs groups, suggesting the implication of this molecule in atherosclerosis." (PMID 23372649, 2013). "In addition, the presence of PF4 and RANTES together is associated with the progression of atherosclerosis and is involved in the vascular remodeling after injury." (PMID 23372649, 2013). "Moreover, introduction of a PF4 null locus, into the ApoE-/- mouse, a well known model of atherosclerosis reduced atherosclerotic lesion formation compared with control mice, thus demonstrating the important role of PF4 in the pathogenesis of atherosclerosis." (PMID 22792197, 2012). "PF4 plays a role in in thrombotic disease or inflammation progress and has anti-heparin activity, may promote the accumulation of deleterious lipoproteins and may promote atherosclerosis." (PMID 28947991, 2017). "LC-MS/MS-based serum proteomic analysis of Atherosclerosis (AS) and Anaphylaxis (AP) mice identified fibronectin 1 (FN1), platelet glycoprotein Ibα chain (GP1BA), and platelet factor 4 (PF4) as candidate biomarkers." (PMID 41828395, 2026). "In the context of inflammatory atherosclerosis, specific macrophage subpopulations have been identified, notably those induced by PF4/CXCL4 and labeled as “M4” (PF4/CXCL4-induced plaque macrophage)." (PMID 40552264, 2025). "Of relevance, the chemokine ligand CXCL4/PF4 inhibits CD163 in macrophages, compromising their phagocytic function and exacerbating the progression of atherosclerosis." (PMID 39611159, 2024).
atherosclerosis (continued). "This was explained by assuming that PF4, TSP-1, and sCD40L are mostly of platelet origin, whereas sP-selectin is primarily released by endothelial cells in patients with advanced atherosclerosis." (PMID 34235190, 2021). "Both PF4 and RANTES are released from α-granules upon platelet activation and hetero-aggregates of PF4 and RANTES promote monocyte adhesion in inflammation or atherosclerosis." (PMID 32630608, 2020). "Although the formation of such chemokine heteromultimers inhibits endothelial cell growth, the disruption of the proinflammatory interaction between the platelet-derived chemokines PF-4 and RANTES also alters monocyte recruitment and inhibits atherosclerosis." (PMID 22384011, 2012). "The present results provide direct evidence that ginkgolide B represses atherosclerosis by attenuating P-selectin, RANTES, CD40L, and PF4 expression in plaque in ApoE−/− mice, with efficacy similar to aspirin." (PMID 22662117, 2012). "Elimination of PF4 reduces atherosclerotic lesion size in ApoE−/− mice and disruption of PF4 and RANTES complexes can also reduce atherosclerosis in this mouse model." (PMID 20454664, 2010). "During infection, inflammatory mediators (e.g., PF4, RANTES) and chemokines released from α-granules promote leukocyte infiltration and inflammation, contributing to the pathogenesis of inflammatory diseases like atherosclerosis and rheumatoid arthritis." (PMID 40137296, 2025). "Our findings may shape a novel strategy for platelet-targeted PF4–TGFβ duet intervention of CD4+ T cell immunity and inflammation in the clinical settings of CD4+ T cell disorders, such as atherosclerosis." (PMID 35437611, 2022).
Sepsis (37 papers, 2009 to 2025). Sepsis is defined as life-threatening organ dysfunction caused by a dysregulated host response to infection. "In sepsis, platelets release antimicrobial peptides (e.g., platelet factor 4 [PF4]), enhance monocyte bactericidal activity, and form microthrombi to limit pathogen dissemination." (PMID 40728969, 2025). "The findings of this study align with those of Wegrzyn, showing the lowest PF4 levels in patients with sepsis who died early." (PMID 40864331, 2025). "In contrast, a novel set of biomarkers, including ACTB, FINC, CXCL7, TIMP1, and PF4, was identified for sepsis prognosis." (PMID 40864331, 2025). "A novel set of biomarkers was identified in this study, including ACTB, FINC, CXCL7, TIMP1, and PF4, for assessing sepsis prognosis." (PMID 40864331, 2025). "Given the complexity of this innate immune response network, our study on 45 patients with sepsis focused on the immune response mediated by platelet PF4." (PMID 32846949, 2020). "Considering the complexity of the innate immune response network, we chose to focus on the immune response mediated by PF4 in a model of sepsis in adults, analyzing the role of anti-GAGs/PF4 IgA-IgG-IgM and the formation of PMPs." (PMID 32846949, 2020). "The bloodusually contains very low amounts of PF4, and only inpathological conditions, such as sepsis and acute tissueinjury, high levels of PF4 release from the activated PLTsinto blood." (PMID 31863655, 2020). "Instead, we found high levels of anti-PF4/GAGS IgA-IgG-IgM antibodies in patients with sepsis, which increased after the onset of the infection." (PMID 32846949, 2020). "The occurrence of IgG-IgA-IgM against PF4-GAGs and PF4+ PMPs correlated with an improvement in patients’ sepsis." (PMID 32846949, 2020). "To ascertain the level of PF4 in our sepsis model and the impact of PKCδ inhibition, we next analyzed the levels of PF4 in plasma samples by ELISA." (PMID 29617417, 2018). "In our model of sepsis, PF4 levels were increased in both the plasma and the BALF of septic animals compared with the sham control." (PMID 29617417, 2018). "Among these are acute-phase reactants such as platelet factor 4, histidine-rich glycoprotein, vitronectin, fibronectin and lipopolysaccharide-binding protein, which increase in sepsis." (PMID 19958532, 2009). "Finally, recent studies demonstrated that PF4, through its stabilizing effect on neutrophil extracellular traps (NETs) that are abundant in sepsis, enhanced entrapment of bacteria." (PMID 37868353, 2023). "Five days after sepsis induction, when splenomegaly was present, we directly imaged the spleen using 2-photon intravital microscopy (2PIVM) and fluorescent reporter mice (Pf4-Cre x mTmG, hereafter called Pf4-mTmG) to visualize MKs and platelets." (PMID 35192546, 2022). "Interestingly, in contrast with the data obtained in KO mice, levels of both PF-4 and Thromboxane upon sepsis were comparable between male and female mice." (PMID 36405709, 2022). "However, the presence of PF4-bearing PMPs appears to correlate specifically with platelet activation secondary to bacterial infection, since we found markedly elevated numbers of PF4+ PMPs solely in patients with sepsis in whom CD62P+PMPs were also increased." (PMID 32846949, 2020). "On the other hand, anti-GAGs/PF4 IgG-IgA-IgM levels were significantly higher in septic patients than in either control group (median OD values in patients with sepsis 0.35, 0.37 at T0 and T1, respectively vs. 0.30 in healthy subjects, and 0.22 in patients without sepsis)." (PMID 32846949, 2020). "The authors concluded that these observations revealed the previously unrecognized involvement of platelet-derived HMGB1 in the regulation of neutrophil recruitment and activation by modulating platelet activation during sepsis, presumably augmented via the participation of PF4." (PMID 33042161, 2020). "To determine whether platelet secretion was altered in the lung during sepsis, we analyzed PF4 content in the BALF." (PMID 29617417, 2018).
Sepsis (continued). "Moreover, PF4 accelerates generation of activated protein C, counteracting the increasing pro-coagulant state during sepsis which may promote DIC." (PMID 31379873, 2019). "Murine studies suggest that PF4 may have an overall salutary effect in sepsis." (PMID 26572220, 2015). "In contrast, ACTB, FINC, TIMP1, PF4, and CXCL7 showed greater potential for predicting sepsis outcomes." (PMID 40864331, 2025). "Further research is needed to elucidate the roles and regulation of PF4 and CXCL7 in sepsis, particularly in bacterial infections and DIC." (PMID 40864331, 2025). "Five key proteins—β-actin (ACTB), fibronectin (FINC), metalloproteinase inhibitor 1 (TIMP1), platelet factor 4 (PF4), and C-X-C motif chemokine 7 (CXCL7)—were identified as significant discriminators of sepsis subgroups with AUCs ranging from 0.786 to 0.833." (PMID 40864331, 2025). "This likely explains why only PF4 and CXCL7 showed significant differences between the healthy cohort and sepsis subgroups among platelet-derived granules." (PMID 40864331, 2025). "Expression of sepsis-specific biomarkers PLXNB3, ITGB3, CETP, CMTM5 and PF4 correlated positively with each other at the Day1 time point and to a slightly lesser degree with MIA and CRP." (PMID 38332914, 2023). "As a potential therapeutic agent in the treatment of sepsis, 2-O, 3-O desulfated heparin (ODSH) reduces histones and platelet factor 4 (PF4) in mouse sepsis models." (PMID 35498738, 2022). "For example, activated PLTs release HMGB1 and PF4 to induce the generation of NETs in thrombotic diseases such as stroke, venous thromboembolism (VTE), and sepsis." (PMID 35869501, 2022). "In the same patients with sepsis, CD62P-bearing PMP numbers were markedly increased and significantly correlated with PF4-bearing PMP (r = 0.564; p = 0.0014)." (PMID 32846949, 2020). "Platelet activation during sepsis triggers the release of RANTES (CCL5) and platelet factor 4 (PF4, CXCL4) and subsequent heteromer formation in the circulation." (PMID 31379873, 2019). "Simultaneously, the platelet-secreted factors TSP, PF4, TIMP-1 and TCK-1 changed significantly during the first 6 h post-CLP and were therefore regarded as meaningful biomarkers of the early stage of sepsis-induced DIC." (PMID 23497204, 2013). "The levels of TIMP1, PF4, and CXCL7 proteins varied across sepsis subgroups in this study." (PMID 40864331, 2025). "A few studies examined the PF4 and CXCL7 levels in patients with sepsis." (PMID 40864331, 2025). "PF4 and CXCL7 levels were decreased with worsening sepsis prognosis." (PMID 40864331, 2025). "When comparing sepsis subgroups based on their outcomes, five key protein markers—β-actin (ACTB), C-X-C motif chemokine 7 (CXCL7), platelet factor 4 (PF4), fibronectin (FINC), and Metalloproteinase Inhibitor 1 (TIMP1)—were identified as significant discriminators." (PMID 40864331, 2025). "In HIT even PF4 knockout mice (that had previously never been exposed to PF4) produced anti-PF4 antibodies when challenged with polymicrobial sepsis." (PMID 37834770, 2023). "While anti-PF4 antibodies are responsible for mediating HIT and are common in patients with sepsis the majority of anti-PF4 antibodies do not induce platelet activation." (PMID 34290613, 2021). "Despite their exposure to heparin, none of our patients with sepsis or hospitalized controls had antibody titers against PF4/GAGs compatible with HIT." (PMID 32846949, 2020). "Anti-GAGs/PF4 IgG-IgA-IgM levels were significantly higher in septic patients than in control groups (healthy controls or acute patients without sepsis, p < 0.001)." (PMID 32846949, 2020). "Patients with and without sepsis were older vs. healthy controls, though anti-PF4/GAGs antibodies are not age-related." (PMID 32846949, 2020). "Although such a translational study has been conducted in sepsis models, the use of PF4 for modulating acute liver injury has not yet been systematically evaluated." (PMID 30971954, 2019).
Sepsis (continued). "Therefore, TSP, PF4, TIMP-1and TCK-1 warrant evaluation as biomarkers of the early stage of sepsis-induced DIC." (PMID 23497204, 2013). "However, unlike the previous study, this analysis revealed that all sepsis subgroups exhibit decreased PF4 levels compared to that of healthy cohorts." (PMID 40864331, 2025). "Transplantation of unlabeled spleens into Pf4-tdTomato recipients with or without sepsis revealed that the majority of splenic MKs were derived from cells outside of the spleen and that this increased after sepsis." (PMID 35192546, 2022). "To test this hypothesis, we prospectively studied the development of anti-PF4/GAGs antibodies in a cohort of 45 consecutive patients with sepsis and a control population (patients without sepsis and healthy volunteers)." (PMID 32846949, 2020). "Sepsis did not appear to affect the titer of anti-PF4/GAGS IgG." (PMID 32846949, 2020). "Among the patients with sepsis in the study by Wegrzyn, non-survivors and those with overt disseminated intravascular coagulation (DIC) display the lowest PF4 levels, suggesting a protective function mediated through macrophage activation." (PMID 40864331, 2025). "Conversely, in blood samples from patients with sepsis, we observed activation of the CXCL pathway along with a notable rise in the ligand PF4." (PMID 38745657, 2024).
systemic sclerosis (34 papers, 2016 to 2025). A chronic disorder, possibly autoimmune, marked by excessive production of collagen which results in hardening and thickening of body tissues. "PF4, a known heparin neutralising factor released from platelets, plays a key role in the activation and differentiation of monocytes and macrophages and is associated with systemic sclerosis and cancer." (PMID 30874579, 2019). "Recent studies have found that PF4 levels are elevated in fibrotic diseases such as systemic sclerosis, chronic liver fibrosis, cystic fibrosis, and myelofibrosis." (PMID 40483519, 2025). "Pf4 is known for its function in triggering monocytes and macrophages to facilitate myofibroblast activation and fibrosis in systemic sclerosis and cancer." (PMID 41008788, 2025). "The macrophage cluster in TSK tumors was significantly rich in platelet-derived factor 4 (Pf4, also known as Cxcl4), an established biomarker in systemic sclerosis." (PMID 41008788, 2025). "Serum PF4 levels were found to be elevated in systemic sclerosis, as well as in the plasma of antiphospholipid syndrome (APS) patients, suggesting its role in the pathogenesis of these disorders." (PMID 35720325, 2022). "Platelet factor 4 (PF4) is identified as a marker for fibrosis, levels of which are elevated in patients with systemic sclerosis and correlated with the presence and progression of pulmonary arterial hypertension." (PMID 32082621, 2019). "For example, PF4 is highly upregulated in dendritic cells after severe trauma or in plasmacitoid dendritic cells in Systemic Sclerosis." (PMID 27223426, 2017). "Furthermore, our study highlights the role of Pf4, a biomarker in systemic sclerosis, as a significantly upregulated gene in macrophages from TSK tumors." (PMID 41008788, 2025). "While speculative, it is interesting to note that a large number of the myeloid cells sequenced highly express PF4 (CXCL4) that is expressed by plasmacytoid dendritic cells and is associated with PAH in patients with systemic sclerosis, although this population might also contain megakaryocytes." (PMID 40569693, 2025). "Thus, targeted inhibition of Pf4 may present a viable strategy for mitigating fibrosis in both systemic sclerosis and cancer." (PMID 41008788, 2025). "PF4 functions in integrin-dependent mechanism controlling angiogenesis, promotes the expression of pro-fibrotic cytokines such as IL-4 and IL-13, enhances the proliferation of regulatory T cells, and plays a role in multiple diseases including systemic sclerosis and antiphospholipid syndrome." (PMID 36091001, 2022). "Anti-PF4 is also detected in several autoimmune diseases (e.g., SLE, systemic sclerosis, and RA)." (PMID 41226302, 2025). "Microcirculation damage, dermal thickening, and difficulty in the spatiotemporal coordination of key platelet factor 4 (CXCL4) and transforming growth factor-β (TGF-β) contribute to the lack of effective treatments for systemic sclerosis (scleroderma, SSc)." (PMID 40558683, 2025).